MIR7704 (microRNA 7704)
Synonyms: hsa-mir-7704
Gene: MicroRNA gene on chromosome 2 (176,188,843 to 176,188,901, forward strand). Ensembl gene ENSG00000283880.
Homologues: Orthologues: chimpanzee MIR7704 (100% identical).